TSPY20P (testis specific protein Y-linked 20, pseudogene)
Gene: Unprocessed pseudogene on chromosome Y (10,036,195 to 10,038,375, forward strand). Ensembl gene ENSG00000243643.
Diseases named in the same sentence as TSPY20P in open-access papers:
TSPY20P is named in the same sentence as 2 diseases in open-access papers, as found by Europe PMC text mining. Sharing a sentence is not in itself a finding about the gene and the disease. The quoted sentences say what the papers report.
adenoma (1 paper, 2024). A neoplasm arising from the epithelium. "Some MP-RNAs interacted with much more partners in adenoma and cancer tissues than in paracancer tissues, such as SLC16A14, POLA2, PCDH11X, TASP1, TSPY20P." (PMID 38773399, 2024).
TSPY20P also shares sentences with these, for which no sentence is quoted: cancer (1 paper).